IGF1 (insulin like growth factor 1)
Diseases named in the same sentence as IGF1 in open-access papers (continued):
Sharing a sentence is not in itself a finding about the gene and the disease.
Stroke (continued). "Sensitivity and specificity test for IGF-1 in diagnosis of stroke illustrated that the probability of being true positive was (78.8%) more than being false positive when repeat test 100 times with sensitivity (70%) and specificity (72%) with cut-off 148.3 ng/ml." (PMID 30595648, 2018). "Given the anti-inflammatory role of miR-424 in the brain of experimental stroke, we further examined TNF-α, IL-10 and IGF1 levels in plasma and determined whether an association existed between plasma cytokines and miR-424 levels." (PMID 29675290, 2018). "This may explain why we found no statistically significant correlative differences in baseline stroke severity between patients with high and low IGF-1 serum levels (correlation between stroke severity and serum level)." (PMID 30595648, 2018). "Moreover, we found that pro-inflammatory cytokine TNF-α level in plasma increased and neurotrophic factor IGF-1 in plasma decreased after stroke, both of which were negatively correlated with miR-424 levels in lymphocytes or neutrophils." (PMID 29675290, 2018). "Similarly, after traumatic, ischemic injury, as observed in the acute stage of stroke, higher IGF-1 levels correlated with a better neurological recovery and physical outcome." (PMID 29149058, 2017). "Additionally, our data show that NaB also an early anti-oxidant effect and a later trophic effect, specifically, elevating IGF-1, which we have previously shown is a robust neuroprotectant for stroke in aging females." (PMID 27905989, 2016). "This study recommends the probable effect of IGF-1 administration on stroke outcome." (PMID 28435630, 2016). "IGF-1 is widely considered neuroprotective in brain injury and stroke." (PMID 24618563, 2014). "A subset of these cytokines including IL-6 was also suppressed by IGF-1 at 24h post-stroke." (PMID 24618563, 2014). "Altogether, our results suggest that the benefit of physical exercise on functional recovery is associated with mitigation of autophagy, attenuation of apoptosis and enhancement of neurogenesis as evidenced by IGF-1 expression and cell proliferation in the peri-infarct region after stroke." (PMID 23565939, 2013). "The authors hypothesized that miRNAs able to target proteins from the insulin-like growth factor-1 (IGF-1) signaling family could be suppressed to promote the neuroprotection provided by IGF-1 following stroke." (PMID 23762086, 2013). "Also, IGF1 and IGF2 levels have been found to associate inversely with ischemic stroke risk in a Danish case-control study, and also with stroke outcome in human studies." (PMID 24373343, 2013). "Using middle-age female rats in which the treatment with estrogen is known to be neurotoxic, the authors administered stereotactically LNA antisense oligonucleotides against miR-1 or let-7f, 4 h after stroke, and observed that miRNA inhibition extended the neuroprotection afforded by IGF-1." (PMID 23762086, 2013). "However, IGF-1 infusion following stroke, prevents estrogen neurotoxicity in middle-aged female rats." (PMID 22393433, 2012). "To identify neuroprotective miRNAs, we used an alternate strategy by interrogating the 3′ UTR of a known neuroprotectant, Insulin-like Growth Factor (IGF)-1, for specific miRNA target sites, with the goal of inhibiting these miRNA to elevate local levels of IGF-1 post-stroke." (PMID 22393433, 2012). "Finally, reduced microglial activation/proliferation resulted in a significant decrease in expression of IGF-1 in microglial cells after stroke." (PMID 22873409, 2012). "IGF1 has been proposed as a potential neuroprotective protein for stroke." (PMID 20667078, 2010). "Unfortunately, we do not have a clear explanation of these facts yet, though it may be that high levels of IGF-1 prior to stroke may reduce tissue responsiveness afterwards, due to negative feedback loops reducing expression of downstream signal receptors." (PMID 21110846, 2010).
Stroke (continued). "Interestingly in a study conducted in elderly patients with stroke, serum IGF-1 levels assessed within 24 hours of the onset of stroke were significantly lower than levels in controls." (PMID 21110846, 2010). "It is also possible that a high level of IGF-1 prior to stroke may be indicative of substantial, but low-level hypoxia in the tissue and that the already stressed neurons are less likely to survive an ischemic event." (PMID 21110846, 2010). "Similarly, in the sub-acute phase after stroke, IGF-1 levels in HFD mice remained higher compared with those in mice fed a standard diet (p=0.051), while treatment with semaglutide in combination with BI8271 resulted in levels that were similar to those in mice fed a standard diet." (PMID 41094027, 2026). "These biological mechanisms provide a rational explanation for our finding: IGF-1 may be more closely associated with long-term neurological remodeling rather than immediate post-stroke injury, consistent with the >1-year subgroup result." (PMID 41586110, 2025). "Indeed, insulin and insulin-like growth factor 1 (IGF-1) have been shown to play a key role in the CNS by regulating neuronal growth and plasticity with multiple effects in the brain, including neuroprotection in cerebral ischemia and stroke patients." (PMID 39062570, 2024). "Moreover, the administration of IGF1 has shown beneficial effects in experimental stroke models." (PMID 36541061, 2023). "In addition, some studies demonstrated that IGF-1 can also play a protective role in the brain of stroke rats, and the lateral ventricular infusion of IGF-1 in post-stroke female rats can reduce the volume of cerebral infarction and inhibit the expression of pro-inflammatory factors." (PMID 37638322, 2023). "Another study found that IGF-1 level was positively correlated with aerobic fitness in acute stroke patients: individuals with higher levels of IGF-1 demonstrated significant improvements in estimated aerobic fitness, which might be beneficial to stroke recovery." (PMID 37371326, 2023). "Given the role of cGP in regulating IGF-1 function, we evaluated the changes in cGP, IGF-1, and IGFBP-3 concentrations in plasma and brain tissues, as well as their association with clinical outcomes in patients with metabolic hypertension, stroke, age-related cognitive impairment, PD, and AD." (PMID 36770687, 2023). "Moreover, the risk of stroke was lowest at the level of 26 nmol/L of IGF-1 and then started to increase rapidly (P for non-linearity < 0.001)." (PMID 37608387, 2023). "Thus, early induction of Zfp580 might inhibit Igf1 and Igfbp3 expression in the acute phase following stroke, but lowering Zfp580 after 3 days may allow Igf1 and Igfbp3 expression through disinhibition." (PMID 35557964, 2022). "Therefore, Zfp580 acts by Igf1 and Igfbp3 on mechanisms highly relevant for stroke outcome." (PMID 35557964, 2022). "However, paracrine cerebral Igf1 was reduced as well, which should worsen recovery after stroke." (PMID 35557964, 2022). "Additionally, enhanced neovascularization and neurogenesis could be the essential mechanisms by which insulin-like growth factor-1 (IGF-1)/IGF-1R improves functional recovery after stroke." (PMID 35883879, 2022). "Altogether, these findings suggest that the circulating ‘youth factors’, like IGF-1, may act as the critical regulator in the systemic proteome and perhaps as the systemic CNS communication to reduce the aging-related acute brain injury after stroke." (PMID 31040201, 2019). "However, it remains to be established whether age in stroke patients could influence the clinical outcome after IGF-1 treatment." (PMID 31920629, 2019). "Thus, the implications of increased expression of Lgals3 at 4 or 8 weeks after stroke may include two aspects: the chronic inflammatory response and the protective effect induced by IGF-1 production after stroke or brain injury." (PMID 31888302, 2019).
Stroke (continued). "Therefore, measuring circulating IGF-1 alone may lead to underestimation of true relationships with incident stroke." (PMID 30595648, 2018). "However, other studies showed an inverse correlation between IGF-1 and stroke severity." (PMID 30595648, 2018). "Therefore, besides the complexity of events related to IGF-1 activity, even when associated with BDNF, for many emerging myokines a possible role as biomarkers in stroke yet needs confirmation in clinical studies, despite the encouraging evidence coming from in vitro or animal studies." (PMID 28373915, 2017). "Delayed actions of NaB may contribute to stroke recovery and repair in two ways: one, by elevating IGF-1 in periphery tissues, which may trigger remodeling responses in both endothelial cells and astrocytes and additionally, by decreasing pro-inflammatory cytokines such as IL-17." (PMID 27905989, 2016). "IGF-1 may protect the blood brain barrier of older animals by directly enhancing survival of endothelial cells, although such actions may be limited during the early phase of stroke." (PMID 24618563, 2014). "Specific cohorts have demonstrated a substantial reduction of 25% in IGF-1 levels and a 40% reduction in IGFBP-3 levels in stroke survivors, compared to healthy controls, indicating a severe deficit in anabolic signaling." (PMID 41598337, 2026). "Angiogenesis is a critical protective mechanism for neuroregeneration after stroke, and stem cell therapies promote it primarily through the bystander effect by secreting growth factors (e.g., VEGF, BDNF, IGF‐1, Ang‐1)." (PMID 41427019, 2025). "Reparative microglia produce neurotrophic factors, including osteopontin (OPN), insulin-like growth factor 1 (IGF1), fibroblast growth factors (FGFs), hepatic growth factor, and growth differentiation factor 15 (GDF15), within a few days following a stroke." (PMID 40098163, 2025). "In post-stroke patients, Åberg observed an increase in the peripheral IGF-1 level during the acute phase of IS and a decrease in the IGF-1 level 3 months after the ischaemic incident." (PMID 40141452, 2025). "Inulin consumption elevated IGF-1 hormone levels in the body, augmented IGF-1 levels in the bloodstream, and stimulated the activation of the MAPK pathway, which alleviated post-stroke depression-like behaviour." (PMID 40458804, 2025). "Based on the obtained results, it is suggested that in the regulation of the expression of GLUT1/GLUT1 during stroke, heat shock protein (HSP) 70, hypoxia-inducible factor (HIF) 1, and insulin-like growth factor-1 (IGF-1) are involved." (PMID 40806521, 2025). "In contrast, other studies, using a rat stroke model, demonstrated that 5 days after the model induction, ICVIGF-1 increased IL-6 plasma concentration, but the intraperitoneal injection of IGF-1 reduced this concentration." (PMID 40801621, 2025). "Previous preclinical studies have shown synergistic effects on decreasing apoptosis and improving behavioral performance after stroke when combining two such trophic factors, erythropoietin (EPO) and insulin-like growth factor-1 (IGF-1)." (PMID 37763230, 2023). "This study also found that IGF-1 treatment inhibited levels of inflammatory cytokines such as TNF-α, IL-1β, and IL-6 at 4 h after stroke, while only IL-6 and IL-13 continued to be inhibited at 24 h after stroke, as did chemokines GRO-KC and CCL2." (PMID 37638322, 2023). "Post-stroke recovery mechanisms remain poorly understood; however, circulating molecules related to neuroplasticity, such as MMP-9, VEGF and IGF-1, can influence the outcome when accompanied by extensive rehabilitation." (PMID 37371326, 2023). "IGF-1 also has a well-known protective role in neuroinflammatory processes and has a protective effect on the BBB in other relevant models such as stroke." (PMID 36755922, 2023). "The same group also demonstrated that deletion of Gal-3 resulted in larger stroke size following MCAO, due to impaired microglial activation and IGF-1 production." (PMID 34831271, 2021).
Stroke (continued). "A 14-residue peptidomimetic of IGF1, bp-1-101, which was able to block the IGF/IGFBP interactions, has been proposed as a therapeutic agent for stroke treatment." (PMID 35178405, 2021). "In proliferating microglia there is co-expression of Galectin-3 and Insulin-like growth factor 1 (IGF-1), while in Galectin-3 KO C57Bl/6 mice there increased protein level of IGF-1 after stroke." (PMID 32455781, 2020). "Moreover, future studies, with larger sample sizes, are recommended to establish the effect of IGF-1 at different time points beyond 24 h of stroke induction, especially with respect to possible short-term confounding effects of the anesthesia before the induction of stroke." (PMID 31920629, 2019). "Two hundred patients with AIS (within the first 24 h) were subjected to full neurological examination, assessment of stroke severity using National Institute of Health Stroke Scale (NIHSS) and measurement of serum IGF-1 levels." (PMID 30595648, 2018). "IGF-1, the only neurotrophic factor that may be regulated by the immune system, has gained great attention in diseases affecting the central nervous system (e.g. depression and stroke) on account of enhancing neuroprotective effects, neuronal survival and plasticity in the brain." (PMID 27527872, 2016). "IGF-1 also induced Akt activation, an effect that was preceded by a reduction of BBB permeability and global suppression of cytokines at 4 h post-stroke." (PMID 25821444, 2015). "To explore the regulatory mechanism of miR-223 in the ischemic pathological process, we also studied the down-stream insulin-like growth factor-1 (IGF-1), IGF1R and IL-6 changes in stroke patients." (PMID 24708646, 2014). "The levels of plasma IGF-1 and IGF1R were greatly increased in the stroke patients group compared to the control group." (PMID 24708646, 2014). "After stroke, microglia in the subventricular zone (SVZ) show a pro-neurogenic phenotype which includes the expression of insulin-like growth factor 1 (IGF-1), another well-known inducer of neurogenesis." (PMID 23386811, 2013). "One possible explanation is that IGF-1 accumulation at the ischemic site is due to influx of peripheral (plasma) IGF-1, gaining access to the brain due to a stroke-weakened blood brain barrier." (PMID 22393433, 2012). "Based on these data, cellular components of the blood-brain barrier may serve as targets of IGF-1 in the aging brain, and IGF-1 supplementation in aged animals and patients may be a useful post-stroke treatment." (PMID 36755922, 2023). "Therefore, the present study examines the expression of VEGF, IGF-1 and MMP-9 proteins and their genes to identify biomarkers that can prognose brain repair ability and thus estimate the outcome of stroke." (PMID 37371326, 2023). "The dose–response analyses yielded U-shaped relationships between IGF-1 concentrations and risks of dementia and stroke (P < 0.001 for non-linearity), with the lowest risks at 18 nmol/L and 26 nmol/L, respectively." (PMID 37608387, 2023). "To investigate whether endogenous cGP is associated with this self-made recovery in stroke patients, we evaluated plasma concentrations of cGP, IGF-1, and IGFBP-3 at the onset of stroke and 3 months post-stroke recovery." (PMID 36770687, 2023). "Previous studies have also noted that changes in IGF-1 serum level are not statistically significant for assessing stroke recovery." (PMID 37371326, 2023). "Hence, the aim of the present study was to evaluate the prognostic value of proteins VEGF, IGF-1 and MMP-9 and the expression of their genes as markers of recovery in stroke patients." (PMID 37371326, 2023). "Astrocytes also produce multiple growth factors such as VEGF, IGF-1, and BDNF, and decreased expression of these growth factors is a feature of aging astrocytes and a possible explanatory factor for the typically severe stroke outcomes seen in older animals." (PMID 34570349, 2022).
Stroke (continued). "Increased numbers of insulin-like growth factor-1 (IGF-1)-expressing microglia have been detected in the subventricular zone (SVZ) at 2, 6, and 16 weeks after stroke, which may mitigate apoptosis and increase the proliferation and differentiation of NSCs." (PMID 36052339, 2022). "Additionally, in humans, stroke and traumatic brain injury (TBI) decrease the levels of IGF-1, but GH therapy improves the speed of processing and memory and decreases the severity of depression, improving the quality of life of patients." (PMID 36232848, 2022). "No sex differences were reported for plasma levels of tissue inhibitor metalloproteinase 1 (TIMP-1) and insulin-like growth factor 1 (IGF-1) 1 day after stroke, matrix metalloproteinase 2 (MMP2) within 2 days after stroke, and matrix metalloproteinase 9 (MMP9) 2 days and 1 month after stroke." (PMID 34858141, 2021). "The anti-inflammatory cytokines most correlated to negative GCS at 5–7 days post stroke include IGF-1 (p = 0.022, r = −0.409), HGF (p = 0.031, r = −0.388), and EGF (p = 0.033, r = −0.384)." (PMID 34360613, 2021). "Another factors identified after stroke and which might directly affect NSC proliferation are, among others, fibroblast growth factor-2 (FGF-2), insulin-like growth factor-1 (IGF-1) and brain-derived neurotrophic factor (BDNF)." (PMID 33834025, 2021). "M2- but not M1-type macrophages have been considered as promising target to enhance angiogenesis and neurovascular unit remodelling after stroke by producing factors such as vascular endothelial growth factor (VEGF), IL-8, Insulin-like growth factor 1 (IGF-1), and TGF-β." (PMID 31281252, 2019). "The IGF-1 treated adult rats also showed significant improvement in sensorimotor function following stroke, while this function was not significantly affected in aged rats." (PMID 31920629, 2019). "It was found that miR-223 expression correlates with stroke subtype (i.e., LA and SA subtype) and negatively correlates with NIHSS scores, but the correlations with infarct volume and insulin-like growth factor 1 (IGF-1) levels were low." (PMID 30563269, 2018). "Moreover, plasma TNF-α and IGF-1 levels increased and decreased, respectively, in stroke patients, and miR-424 levels in lymphocytes and neutrophils were both inversely correlated with plasma TNF-α, IL-10, or IGF-1 levels." (PMID 29675290, 2018). "Ischemia significantly increased brain IGF-1 levels at 2d post stroke, however, brain IGF-1 levels were not affected by NaB treatment [F, 2.19, p = 0.1697]." (PMID 27905989, 2016). "Unlike its action on lipid peroxides and IGF-1, NaB suppression of inflammatory cytokines spanned the early and late acute phase of stroke." (PMID 27905989, 2016). "No significant alteration was observed in IGF-1 levels from serum, liver, and spleen between groups at 2 days post stroke." (PMID 27905989, 2016). "IGF-1 upregulation through exercise is also being explored in animal stroke models as well as non-ischemic human studies." (PMID 25942688, 2015). "While IGF-1 mediated Akt activation has been shown in a neonatal model of hypoxia-ischemia, the present study is the first to show that IGF-1 elevates pAkt in an aging stroke model." (PMID 24618563, 2014). "Although Let7f has a consensus binding site on the IGF-1 3′UTR, ICV infusions of anti-Let7f did not elevate IGF-1 mRNA or protein levels in ischemic tissue when measured 5 days post-stroke." (PMID 22393433, 2012). "Presumably these patients had low levels of IGF-1 before stroke, though this has not been established." (PMID 21110846, 2010). "This is followed by a description of post-stroke angiogenesis and its relationship to neuroregeneration and its modulation by vascular endothelial growth factor (VEGF) and insulin-like growth factor 1 (IGF 1), the most important factors active in old brain after ischemic injury." (PMID 21110846, 2010).